CD36 (CD36 molecule (CD36 blood group))
Diseases named in the same sentence as CD36 in open-access papers (continued):
Sharing a sentence is not in itself a finding about the gene and the disease.
diabetes (continued). "CD36 binds long-chain fatty acids and facilitates their transport into cells, thus participating in muscle lipid utilization, adipose energy storage, and gut fat absorption and possibly contributing to the pathogenesis of metabolic disorders, such as diabetes and obesity." (PMID 28202906, 2017). "This study demonstrated that diabetes and HG stimulation downregulate APT1-dependent depalmitoylation of CD36, thereby enhancing CD36-mediated fatty acid uptake." (PMID 40607256, 2025). "This study aims to investigate the effects of hyperglycemia on the gene and protein expression of CD36, CD69, CD274, and TLR-7 during wound healing using a rat model of induced diabetes." (PMID 41465460, 2025). "Our data showed increased cholesterol uptake genes (FABP1, CD36, and SRA1) in diabetes, which was in an agreement with recently published studies." (PMID 36829889, 2023). "Whereas in diabetes, the enhancement of insulin strongly activates the PI3K-Akt (phosphatidylinositol 3‐kinase-protein kinase B) pathway that leads to a robust CD36 expression." (PMID 35396566, 2022). "Upon the development of diabetes, cardiomyocytes absorb more FFA to provide energy through FAs transferase CD36; however, excessive FAs uptake damages mitochondrial FAO, leading to mitochondrial dysfunction and lipid accumulation." (PMID 34249132, 2021). "Muscle aging (Atrogin 1 and Glb1), diabetes (RAGE and CD163), and intracellular lipid accumulation (CD36 and PPARγ) related mRNA and protein expressions and FMOD were analyzed in MSTN knockout gas muscles." (PMID 34440852, 2021). "Alterations in lipid metabolism are present in both STZ-T1DM and T2DM, but therapeutic targets on lipid metabolism, such as PPAR agonists or CD36 antagonists, to prevent diabetes-induced TIF should be adapted to the diabetes type." (PMID 35052710, 2021). "Numerous studies have reported that CD36 is closely related to the development of Mets, atherosclerosis, NAFLD and diabetes." (PMID 33995128, 2021). "Another condition that could affect CD36 levels is the number of MP with which this molecule is associated, e.g., fatty acid transporter CD36 related to platelet-derived MP may be increased in proportion to these cell particles in subjects without diabetes." (PMID 32498389, 2020). "The role of CD36 in infection of Plasmodium falciparum and atherosclerosis and cardiovascular disease has attracted the most interest; however, more recently there has been an increased focus on its role in diabetes mellitus (DM)." (PMID 32796572, 2020). "It has been reported that, in diabetes, increased scavenger receptor of modified LDL (CD36) and reductions in the levels of ATP binding cassette (ABC) transporters (ABCA1 and ABCG1), increase macrophage foam cell formation." (PMID 26807573, 2016). "Much evidence indicates that the level of the scavenger receptor CD36 increases and those of ABC transporters (such as ABCA1 and ABCG1) decrease significantly in patients with diabetes and vascular complications thereof, such as atherosclerosis." (PMID 26807573, 2016). "N-Acetylcysteine restored Sevo-postC cardioprotection in diabetes possibly through enhancing cardiac p-STAT3 and adiponectin and reducing Fox1 and CD36." (PMID 26783539, 2016). "Cardiac CD36 expression was elevated from 2 months in WT diabetic mice and from 1 month in FGF21KO diabetic mice after diabetes onset." (PMID 25823710, 2015). "The mRNA expression levels of FAT/CD36, FABP1, and FATP5 in diabetes group were higher than those in control group." (PMID 23691525, 2013). "In diabetes, the increased sarcolemmal abundance of FAT/CD36 has been shown to be a result of impaired recycling between intracellular storage compartments and the sarcolemma." (PMID 21494549, 2011). "Foam cell formation and CD36 gene expression were enhanced in monocyte-driven macrophages extracted from patients with diabetes mellitus in comparison to those from non-diabetic healthy subjects." (PMID 39273671, 2024).
diabetes (continued). "Next, we explored the differences in Cd36+ KCs under the influence of diabetes and non-diabetes conditions." (PMID 39494341, 2024). "Intriguingly, correlation analysis showed a significant association between PPARδ, but not CD36, and CCL2, therein implicating subclinical inflammatory potentiation of monocytic cells in patients with diabetes." (PMID 38989454, 2024). "Given the well-established molecular link between Sirt1 and PPARG signaling and the detrimental role played by PPARG in the context of MCM, we examined PPARG and PPARG-dependent genes LPL, PLIN, CD36, FAS and PPARA in cardiac specimens from diabetics and controls." (PMID 37957697, 2023). "The allelic frequencies and genotype distribution of the different CD36 SNPs (rs1761667 and rs3211867) were not significantly different regardless of the considered group (control or diabetes group)." (PMID 36031603, 2022). "In the current work, the platelet CD36 protein level was found to be higher in overweight NVAF patients than in normal weight patients regardless of hypertension, coronary artery disease, heart failure, and diabetes mellitus." (PMID 36465448, 2022). "We noted a nonsignificant increase in sCD36 levels in subjects with diabetes with CD36 gene methylation compared to control subjects with CD36 gene methylation (p = 0.27)." (PMID 36031603, 2022). "The purpose of this study was to explore the potential mechanism of improving IR and reducing diabetes and its complications by investigating the effect of LR on lipotoxicity-induced changes in the expression of FAT/CD36, FABP4, GRP78, and GLUT4 in rat skeletal muscle L6 myoblasts." (PMID 36619308, 2022). "This difference was not significant in the type 2 diabetes group comparing subjects with diabetes with CD36 gene methylation to subjects with diabetes without CD36 gene methylation (p = 0.09)." (PMID 36031603, 2022). "Despite the beneficial impact of CD36 ablation on several metabolic stresses, direct effects of CD36 deletion on cardiac function in diabetes have not been explored in vivo." (PMID 34940639, 2021). "FGF21 deletion had no obvious effects on cardiac CD36 expression under basal conditions, but diabetes significantly up-regulated CD36 expression in both WT and FGF21KO hearts." (PMID 25823710, 2015). "For example, determine whether acute overexpression of O-GlcNAcase, which has been shown reverse some of the adverse effects of diabetes on cardiac function, would also reduce sarcolemmal FAT/CD36 levels thereby reverse the metabolic dysfunction." (PMID 21494549, 2011). "Clearly future studies are warranted to determine whether O-GlcNAc levels of FAT/CD36 are indeed increased in diabetes and if so, whether this is a contributing factor in the increased levels of sarcolemmal FAT/CD36." (PMID 21494549, 2011). "These increases in LCFA transport in heart were associated with concomitant increases in the expression of FAT/CD36 and FABPpm proteins, which resulted in the increased presence of FAT/CD36 (moderate and severe diabetes) and FABPpm (severe diabetes only) at the sarcolemma." (PMID 19924273, 2008). "Additionally, using peripheral blood mononuclear cells (PBMCs) from patients with or without diabetes, we show that pharmacological inhibition of PPARδ, but not CD36, mitigates HKMT-induced inflammatory responses." (PMID 38989454, 2024). "In addition, the dynamic impact of CD36 in the progression from IR to diabetes has not been elucidated." (PMID 36979708, 2023). "Accordingly, limited FA use from CD36 ablation could contribute to the deterioration of contractile dysfunction in diabetes, rather than to the protection from lipotoxic effects." (PMID 34940639, 2021). "However, conclusive in vivo studies indicating a causal link between expression levels/subcellular localization of CD36 and cardiac function in diabetes have never been demonstrated." (PMID 34940639, 2021).
diabetes (continued). "The effect of added oleic acid in the context of reduced but not absent CD36 could perhaps lead to an insulin-resistant state, and similar to in diabetics, inhibits vessel formation, even in the context of pro-angiogenic signals." (PMID 34888367, 2021). "We aimed to determine whether CD36 expression was altered in carotid plaques from subjects with diabetes (n = 15) when compared with plaques from subjects without diabetes (n = 15)." (PMID 33028031, 2020). "In addition, CD36 and Slc27a4/Fatp4 expression levels, while not influenced by diabetes, were strongly responsive to diet (40.6% and 82.1%, respectively)." (PMID 31774824, 2019). "However, the roles of APN, FoxO1, and CD36 in sevo-postC with or without NAC pretreatment in diabetes have not been studied." (PMID 26783539, 2016). "Therefore, we implement NAC treatment to 8-week diabetic rats during feeding period and sevo-postC before reperfusion to test the hypothesis that NAC and sevo-postC can synergistically reduce myocardial IRI in diabetes and explore the roles of p-STAT3, FoxO1, APN, and CD36 in this procedure." (PMID 26783539, 2016). "It is relatively well established that diabetes also increases overall cardiac O-GlcNAc levels; it is possible, therefore, that in the diabetic heart O-GlcNAcylation of FAT/CD36 may shift the balance towards sarcolemmal localization of FAT/CD36 possibly by inhibiting recycling." (PMID 21494549, 2011). "We then isolated PBMCs from individuals with or without diabetes and pretreated them with either SSO to inhibit CD36 or GSK3787 to inhibit PPARδ before exposing them to HKMT." (PMID 38989454, 2024). "Increased CD36 and FABP4 immunostaining were detected in kidney specimens from diabetic patients vs. those without diabetes (respectively) and confirmed via quantitation of immunostaining, respectively)." (PMID 37760019, 2023). "We analyzed the mRNA expression of SRs (LOX-1, MSR1, CXCL16, CD36 and CL-P1) and macrophage markers (CD68, CD11c and CD206) in EAT from 45 patients with IHD (23 with type 2 diabetes mellitus (T2DM) and 22 without T2DM) and 23 controls without IHD or T2DM." (PMID 30894181, 2019). "Importantly, we showed elevated gene expression of PPARδ, CD36, and CCL2 in monocytic cells from OB individuals with diabetes compared with those without." (PMID 38989454, 2024). "Platelet CD36 could serve as a mediator of overweight and prothrombotic state in NVAF patients, regardless of hypertension, diabetes, coronary artery disease, and heart failure." (PMID 36465448, 2022).
malaria (129 papers, 2007 to 2025). Malaria is a serious and sometimes fatal disease caused by a parasite that commonly infects a certain type of mosquito which feeds on humans. "Most UPSB and UPSC var genes encode PfEMP1s that bind CD36 through their CIDRα2–6 domains, and have been linked to uncomplicated malaria." (PMID 40493675, 2025). "In the P. berghei ANKA malaria model, CD36 expression has been linked to lung parasite sequestration, resulting in acute lung injury and heightened mortality." (PMID 39300444, 2024). "Instead, CD36 attachment is linked with uncomplicated malaria, and seems to have been formed to promote IE sequestration in tissues other than the cortex, where CD36 is missing or only sparkling." (PMID 35715862, 2022). "In particular, CD36 has been linked to cytoadherence phenotypes in severe malaria (33, 42, –, 44) and malarial lung injury in particular, the latter via signaling through kinases involved cytoskeletal and junctional remodeling." (PMID 33563839, 2021). "This is supported by the observation that individuals carrying a CD36 nonsense mutation are protected from malaria-induced anemia that was linked to augmented erythrophagocytosis." (PMID 34573346, 2021). "This is in concordance with all three other adult studies also indicating a substantial expression of B- and C-type variants associated with the binding of CD36, and even showed an association with complicated adult malaria." (PMID 33908865, 2021). "Proinflammatory signaling is induced, and key cytoadherence molecules are upregulated, including several associated with severe malaria, such as CD36 and ICAM1." (PMID 33563839, 2021). "CD36 has also been implicated in hemostasis, thrombosis, malaria, inflammation, lipid metabolism, and atherogenesis." (PMID 31212896, 2019). "Genetic variants that show disparate roles in malaria pathogenesis depending on their homo/heterozygous state (e.g., CD36)." (PMID 31417551, 2019). "Genetic modifications of CD36 have been investigated thoroughly since the identification of malaria-predisposing mutations." (PMID 31379931, 2019). "In P. falciparum endemic regions, single nucleotide polymorphisms in the Cd36 gene have been linked to protection from cerebral and other severe malaria." (PMID 30619355, 2018). "Conversely, transcripts encoding PfEMP1 predicted to bind CD36, which are also found in highest number in the parasite genome, dominated in the patients with uncomplicated malaria." (PMID 27354391, 2016). "Experiments with both monoclonal anti-CD36 antibodies and CD36-deficient rodent macrophages have shown that CD36 plays also a role in phagocytic uptake of RBC in malaria." (PMID 28018860, 2016). "It was recently discovered that many people of African origin harbor a high frequency of mutations and single-nucleotide polymorphisms (SNPs) that cause a deficiency in the CD36 gene, yet they still suffer from severe (particularly cerebral) malaria." (PMID 23487416, 2013). "People in malaria endemic areas have been shown to have a relatively high frequency of Cd36 mutations and that these mutations contribute differently to the outcome of malaria infection." (PMID 24204889, 2013). "The high case fatality rate syndromes of cerebral malaria and lactic acidosis were associated with high platelet CD36 expression and thrombocytopenia, and severe malaria anaemia was characterized by low ICAM1 expression." (PMID 22909232, 2012). "These mutations that cause CD36 deficiency are associated with susceptibility to severe malaria and cerebral malaria." (PMID 22287954, 2012). "Our results show that increased binding to CD36 is associated with uncomplicated malaria while ICAM-1 adhesion is raised in parasites from cerebral malaria cases." (PMID 21390226, 2011). "Additional studies are required to clarify the association between CD36 polymorphisms and severe malaria including ALI." (PMID 18483551, 2008).
malaria (continued). "In a study in Kenya, a mutation in the CD36 gene among children has been associated with protection from severe malaria." (PMID 18844973, 2008). "Association of the ICAM1 rs5498 (exon 6) G allele and the CD36 exon 1a A allele with increased risk of severe malaria was observed (severe versus control, OR = 1.91 and 2.66, P = 0.02 and 0.0012, respectively)." (PMID 19055786, 2008). "Notably, CD36 deficiency or reduced surface expression confers partial protection against malaria by significantly decreasing IE cytoadherence." (PMID 41450567, 2025). "However, despite the observed associations between CD36 polymorphisms and malaria severity, there remains limited evidence directly linking these genetic variations to malaria-driven selection." (PMID 40993672, 2025). "The high frequency of CD36 mutations in African and Asian populations may have been shaped by selective pressures unrelated to malaria." (PMID 40993672, 2025). "All these observations underline the importance of CD36 for malaria." (PMID 36557610, 2022). "Additionally, seroreactivity changes were more pronounced for CD36-binding and CD36-associated PfEMP1 fragments across the dry and malaria transmission seasons than they were for EPCR/ICAM-1-binding PfEMP1s, but this was not the case across the entire year." (PMID 34257318, 2021). "CD36 knockout mice were more susceptible to severe malaria with earlier spikes in parasitemia and increased mortality, highlighting the importance of this signaling pathway for host defense against malaria." (PMID 34335547, 2021). "It has been suggested that mutations causing deficiency of the scavenger receptor CD36 in African and East Asian populations may have been selected to protect against malaria." (PMID 34070159, 2021). "CD36 is also important for host resistance to infection, and its deficiency significantly reduces mycobacteria burden, whereas its induction helps control severe malaria through parasite clearance." (PMID 34722338, 2021). "Almost all P. falciparum isolates bind to CD36, and increased CD36 binding and predominant expression of group B and C PfEMP1 are associated with uncomplicated malaria." (PMID 31455446, 2020). "Village-level prevalence of the CD36 polymorphism (rs3211938) was associated with all 3 transmission intensity measures and with the principal component representing putative long-term effects of malaria exposure." (PMID 28541483, 2017). "Consistent with this idea, in a mouse malaria infection model, the deficiency in CD36 was found to be associated with significantly lower inflammatory cytokine responses, lower parasite clearance, elevated parasitemia, and increased malaria severity and fatality." (PMID 24204889, 2013). "Furthermore, Cd36 mutations in endemic population have been shown to contribute to either protection from severe malaria or susceptibility to illness, which presumably depends on host factors and infection dynamics." (PMID 24204889, 2013). "In addition, the influence of genetic polymorphisms for proteins involved in phagocytosis can be investigated using this assay, in particular, those known to be associated with protection from severe malaria (for example CD36 and FcRs)." (PMID 22675573, 2012). "Furthermore, the class B family of scavenger receptor CD36 on macrophages is also implied in protection against malaria, since CD36-deficient individuals are at a greater risk of developing severe and cerebral malaria." (PMID 22348301, 2012). "Moreover, some cytoadherence phenotypes, such as adhesion to CD36, have been associated with uncomplicated malaria, suggesting a protective role in the context of severe disease." (PMID 21559373, 2011). "To determine whether the PGN-induced increase in parasite burden observed in our severe malaria model was associated with macrophage CD36 downregulation, we evaluated the CD36 protein level on peritoneal macrophages." (PMID 21949655, 2011).